MAX (MYC associated transcriptional regulator X)
Diseases named in the same sentence as MAX in open-access papers (continued):
Sharing a sentence is not in itself a finding about the gene and the disease.
tumor (continued). "The small protein ME47 disrupts the MAX:E-box interaction, leading to a block of MYC/MAX transcription and inhibition of tumor growth." (PMID 36969025, 2023). "Our findings demonstrate that the small-molecule MYCMI-7 binds MYC and inhibits interaction between MYC and MAX, thereby hampering MYC-driven tumor cell growth in culture and in vivo while sparing normal cells." (PMID 36874405, 2022). "MXD1 is a tumor suppressor and functions to compete with MYC for interacting with MAX to form a transcription repressor of the MXD1-MAX." (PMID 36167790, 2022). "Focally deleted regions identified the tumour-suppressor genes RHOA at 3p21, CDKN2A and CDKN2B at 9p21, RAD51B, MAX, DICER1, BCL11B, NKX2-1, CCNB1IP1 and BAZ1A at 9q33." (PMID 34980126, 2022). "To verify that MYCMI-7 inhibits MYC:MAX dimerization in tumor cells, we utilized the split Gaussia princeps luciferase (GLuc) assay, with GLuc fragments GLuc1 and GLuc2 fused to MYC (or MYCN) and MAX, respectively, in HeLa cells." (PMID 36874405, 2022). "In summary, we show that MYCMI-7 is a direct MYC-binding compound that potently and selectively inhibits MYC:MAX interaction and MYC-mediated gene regulation and tumor cell growth in a MYC-dependent manner in culture and in vivo, while sparing normal cells." (PMID 36874405, 2022). "MXD3 is a transcription factor belonging to the MYC/MAX/MXD transcriptional network, and its expression is increased in tumor tissues." (PMID 34671559, 2021). "We determined MAX, MGA, MYC, L3MBTL2, E2F6, and RNA polymerase II (RNA pol2, all phosphorylated forms) occupancy in Mga-inactivated and control (empty) KP tumor-derived cells lines." (PMID 34236315, 2021). "The classic role of MGA was a TSG that suppressed the progress of tumors by binding to MAX and inhibiting MYC-dependent tumor development." (PMID 34733843, 2021). "As part of the MYC/MAX/MXD1 network, MXD1 and MYC compete for binding to MAX, so enhanced MXD1 expression suppresses tumor growth, consistent with our finding here." (PMID 34830961, 2021). "MAX expression in HCC activates Linc00176, which is a competing endogenous lncRNA (ceRNA) of tumor-suppressive miRNA, resulting in cell cycle acceleration and reduction of apoptosis by reducing the levels of miR-9 and miR-185." (PMID 32102656, 2020). "Somatic mutations in inherited PCC/PGL genes can be detected in ~25–30% of the sporadic tumours (mainly involving RET, VHL, NF1, MAX, and HIF2A genes)." (PMID 25883647, 2015). "The SP1, MAX, RUNX1 and STAT3 sub-networks are involved in both early and late stages of the tumor but are expressed with different gene expressions." (PMID 20025723, 2009). "We suggest that the transcription factors SMAD3/4, GNB2L1/RACK1, MYC, MAX and JUN, whose functions have been extensively studied in tumours but only marginally in muscle, appear instead to play important roles in regulating muscle response to atrophy." (PMID 19108710, 2008). "A recent study has also shown that although MAX inactivation can accelerate SCLC progression, this effect is independent of MYC, and MAX deletion in MYC-overexpressing SCLC also leads to tumor abrogation." (PMID 38992040, 2024). "Furthermore, it inhibits MYC/MAX interaction and induces apoptosis in tumor tissue derived from a MYC-driven xenograft tumor model." (PMID 36969025, 2023). "MAX, DCAF7, and STMN1 were identified as novel targets of miR-193a, which may contribute to its anti-tumor effect." (PMID 37443682, 2023). "Interestingly, CX-4945 treatment lowered HMGB1, β-catenin, C-MYC, phosphor-MAX, IL-6, and CSNK2A1 protein levels in tumor tissues in CX-4945 treatment as compared with a vehicle." (PMID 37347224, 2023). "Similarly, after their culture with ECs, IL30-overexpressing PCs showed a dramatic upregulation of a wide range of oncogenes, which included CCND2, EGR3, IGFBP5, KLK3, PDLIM4, PTGS1 and SHBG and a few tumor suppressors, such as GPX3, FOXO1, MAX and NKX3-1." (PMID 38087324, 2023).
tumor (continued). "On the contrary, should we target the MYC-MAX complex, we would have success in all the cases but in 2 RMS and in 1 WT in which MAX is not expressed in all the samples of the tumor mass." (PMID 36284197, 2022). "However, when tumor cells are hypoxic, HIF1α can inhibit the transcription of ODC by binding to MAX and inducing the binding of MAX-interacting protein (MXI1) with MAX." (PMID 35912204, 2022). "In four tumors with multiple biopsies, percentages ranged from 0 to 30% mutant allele per each case, while complete allele loss (LOH) for markers on chromosome 11p or 16q assured high tumor cell content even for MAX wild-type specimens (data not shown)." (PMID 34689785, 2021). "MGA is a tumor suppressor gene (TSG) that binds to MAX and inhibits MYC-dependent tumor growth." (PMID 34733843, 2021). "MGA, MAX, E2F6, and L3MBTL2 were seen to bind several thousand promoters in MGA-expressing KP tumor cells suggesting that the PRC1.6 complex plays a broad role in tumor cell gene expression." (PMID 34236315, 2021). "MAX, DCAF7, and STMN1 were identified as novel targets of miR-193a that could contribute to its tumor-suppressive effect." (PMID 32410663, 2020). "In summary, administration of MYCMI-6 to MYCN-dependent tumor-bearing mice resulted in the reduction of MYCN:MAX interaction, tumor cell proliferation and MVD and in induction of apoptosis in the tumor tissue without causing severe side effects." (PMID 29968736, 2018). "Further, it inhibits MYC:MAX interaction, reduces proliferation and induces massive apoptosis in tumor tissue from a MYC-driven xenograft tumor model without severe side effects." (PMID 29968736, 2018). "Different types of endogenous MYC/MAX complex antagonists, such as MAX/MAX, MAD/-MAX and Mnt1/MAX, have been found to downregulate transcription of MYC genes, and could serve as potential anti-tumor agents." (PMID 26858789, 2016). "This suggests a potential regulatory relationship between MAX, MXI1, and DNA methylation that may extend to downstream cancer tumor development." (PMID 25616342, 2015). "In a previous report, we demonstrated that KSI-3716, which inhibits c-Myc/MAX/DNA complex formation, can be instilled into the bladder to effectively suppress tumor growth without noticeable systemic toxicity, demonstrating a novel use for c-Myc inhibitors." (PMID 24504118, 2014). "Therefore, the over-expression of MGA by the knockdown of P(RR) will curtail the supply of MAX for MYC heterodimerization and stop the MYC-dependent cellular processes from shifting tumor cells from a rapidly dividing state to a more regulated state of division." (PMID 37869088, 2023). "These four mechanisms—MYC genomic gain (9% of O1 tumours), MAX genomic loss (35% of O1 tumours), MYC exon 3 hypomethylation (20% of O1 tumours) and mir34b/c locus hypermethylation (28% of O1 tumours)—were not all required to observe an increase of MYC activity." (PMID 27090007, 2016). "Staining of the GIST from the patient’s earlier resection confirmed complete absence of MAX and strong plasma membrane staining for KIT in the tumor." (PMID 26555092, 2015). "Therefore, TAF1 is a hub gene in both the normal and tumor lists, while HNF4A, MAX, and MYC are not." (PMID 35428183, 2022). "Therefore overexpression of MGA, caused by (P)RR knockdown, could disturb this balance, limiting the supply of MAX for MYC heterodimerization and antagonizing MYC-dependent cell processes; re-routing the tumour cell from a proliferative to a non-proliferative state." (PMID 35401936, 2022).
cancer (106 papers, 2005 to 2026). A tumor composed of atypical neoplastic, often pleomorphic cells that invade other tissues. "While somatic inactivating mutations in MAX have been identified in a number of cancers, to date few germline pathogenic variants in MAX have been identified." (PMID 38141607, 2024). "MYC is overexpressed in many different types of cancers, and its endogenous and pathogenic function is completely dependent on the interaction with its partner protein MAX, as only the heterodimer can bind DNA." (PMID 32225120, 2020). "Five cancer genes mutated at greater frequency in AA LUAD tumors (MAX, ACTN2, PRKD1, PTPRC, STK11) remained significant after accounting for mutation burden and age at diagnosis." (PMID 32952607, 2020). "In cancer, this led to imply the TF Myc-associated factor X (MAX) in modulating ATF4 and CLOCK interaction." (PMID 33322692, 2020). "Targeted sequencing of 812 cancer-associated genes demonstrated somatic homozygous inactivating MAX mutations in three of ten GISTs." (PMID 28270683, 2017). "A close follow-up for both recurrent PPGL and other types of malignant tumors is essential for the patients with MAX mutation." (PMID 29282558, 2017). "Due to the possibility for other types of malignant tumors, close follow-up is essential for MAX mutation carriers." (PMID 29282558, 2017). "In contrast, of the small number of MAX mutation carriers, 9% (1/11) had a malignant tumor, with the only SDHAF2 mutation carrier being devoid of malignant disease." (PMID 28752085, 2017). "In the literature, two in 19 PPGL patients with MAX mutations had cancers, breast cancer, and squamous cell carcinoma of the tongue." (PMID 29282558, 2017). "The patients of PPGL with MAX mutation need a close follow-up for not only recurrence of PPGL but also emergence of other malignant tumors." (PMID 29282558, 2017). "As many Mendelian disorders are rare and highly penetrant, it is common to compare the frequency of variants to population-matched controls from public databases, as exemplified by studies that identified the cancer predisposition genes MAX and POLD1/POLE." (PMID 27279102, 2016). "Also, some of the recently discovered cancer predisposing genes appear to act in accordance with this scenario, such as for instance the MAX, SMARCE1 and BAP1 genes." (PMID 27279102, 2016). "Similar considerations may underlie the impact of Omomyc on MAX protein levels in cancer cells." (PMID 36830948, 2023). "Among them, we discover the master regulators MYC and MAX that play central roles in cell (de)differentiation and cancer progression to read hmC in a sequence-dependent manner." (PMID 41486423, 2026). "One of most relevantchallenges in tumorigenesis is theassociationof MYC and MAX proteins, whose related cancers remain undrugged." (PMID 41456320, 2026). "Compounds that target the MYC/MAX interaction have some effect in cancer, though these inhibitors often suffer from limited potency and significant off-target effects." (PMID 41002386, 2025). "Overall, a germline pathogenic variant (gPV) in a cancer predisposing gene was identified in 9.7% of individuals (CHEK2, FANCM, NF1, POT1 and PTEN) and a candidate variant in 4.2% of individuals (HOXB13, MAX and RECQL4)." (PMID 39979679, 2025). "This is mostly driven by the cancer-related TF MAX whose binding is antagonized by many other bHLH TFs such as MNT, MXD1, and MXD4." (PMID 39013578, 2024). "Specifically, 10058-F4 inhibited MYC/MAX heterodimerization and demonstrated cytotoxic activity and apoptosis induction activities in a variety of cancer cell lines." (PMID 37111592, 2023). "We also performed Co-IP with human CCA and normal human liver lysates and found higher levels of MAX interaction and more interaction with β-catenin in the cancer tissues." (PMID 37347224, 2023).
cancer (continued). "MYC overexpression in cancer cells contributes to the formation of a high number of MYC/MAX dimers that invade transcriptionally active chromatin sites." (PMID 36830948, 2023). "As a whole, these data showed that MAX is also required for miR-22 to attenuate glycolysis and cancer stem cell transcription factors in CRC cells." (PMID 36061355, 2022). "Specifically, WTAP inhibits MXD2 expression by m6A modification, leading to increased binding of cMyc to MAX, which promotes cMyc transcriptional activity and mTORC1-activated cancer cell proliferation." (PMID 36139062, 2022). "MYC is one of the well-known oncogenes, contributing to the development and progression of cancer and functions through interaction with MAX." (PMID 36167790, 2022). "We also identified medically actionable variants in eight other cancer-related SFs genes, including APC, MAX, MSH6, MLH1, PALB2, PMS2, SDHB, and TSC2." (PMID 36143288, 2022). "We also determined the impacts of miR-22 and MAX on the glycolysis and cancer stem cell transcription factors in CRC cells." (PMID 36061355, 2022). "Indirect targeting of MYCN using small molecule inhibitors such as bromodomain inhibitors and inhibitors that disrupt the interaction between MYC and its binding partner, MAX has been explored in different cancers." (PMID 34680394, 2021). "Peptidomimetics that disrupt MYC/MAX dimerization have shown efficacy in in vivo cancer model systems." (PMID 32225120, 2020). "We conclude that the cancer-associated transcription factors YY1 and MAX exhibit expressional heterogeneity in FTCs." (PMID 33063251, 2020). "Similar to our observations in diverse cancer cell lines, MAX silencing increased the levels of clock transcripts in both BJ-5ta and MCF10A." (PMID 32225100, 2020). "Immunostaining of candidate proteins MAX, TCF7L2, YY1, IRF1, STAT6, SP1, and E2F1 (selected based on qPCR results and/or associations to cancer in general) was performed in additional FTC specimens as outlined in the “Materials and Methods” section." (PMID 33063251, 2020). "MXD1 is a MYC inhibitor and competes with MAX, a co-activator, with this MYC/MXD1/MAX signaling pathway being implicated in the development of some types of cancer." (PMID 31261609, 2019). "One of the major signaling pathways involved in cancer progression is the MYC/MAX/MAD network, which is related to cell growth, proliferation, differentiation, and apoptosis." (PMID 29383100, 2017). "Mechanistically, MBZ can modulate the cancer-associated pathways including ELK1/SRF, AP1, STAT1/2, MYC/MAX, although the regulatory outcomes are context-dependent." (PMID 28099902, 2017). "By using a panel of previously well-characterized cancer-associated pathway reporter analyses, we found at least four pathways, e.g., ELK1/SRF, AP1, STAT1/2, MYC/MAX, are significantly affected." (PMID 28099902, 2017). "Of note, variability and especially measured by MAX/MIN is significantly greater in cancer tissues, reflecting expression deregulation." (PMID 19526064, 2009). "We conducted a separate analysis for the cancer-associated genes RET and MAX." (PMID 39301547, 2024). "Importantly, HIF2A-induced stabilization of MYC/MAX heterodimer is much stronger than HIF1A-mediated degradation of MYC in human cancer cells, leading to MYC activation under hypoxia." (PMID 37998757, 2023). "Therefore, it is not surprising that MYC inhibition represents an attractive strategy against many cancer types MYC dimerizes with MAX through the bHLHZip domain." (PMID 36830948, 2023). "The enhanced stability of MAX in cancer cells led us to examine whether it regulated cell proliferation." (PMID 37347224, 2023).
cancer (continued). "Thus, WTAP inhibitors can increase MXD2 expression, leading to reduced cMyc binding to MAX, thereby inhibiting mTORC1-activated cancer cell proliferation." (PMID 36139062, 2022). "Focal adhesion, cAMP signaling pathways, and pathways in cancer were also under the most upregulated KEGG pathways in PPGLs with EPAS1 mutation compared with tumors bearing a mutation in one of the cluster 2 susceptibility genes (NF1, RET, MAX)." (PMID 35159368, 2022). "The indispensable genes are directly associated with cancers, especially EGFR, MAX, MNT, SMAD3." (PMID 33968733, 2021). "MAX (a MYC interacting partner), miR-150, miR-133a, FOLR1, E2F NCAM1, GAS2L3 and ATF5 are the most significantly associated upstream regulators, while cancer, neurogenesis, metastasis and cellular development are the most important biological functions affected in this subgroup." (PMID 32591022, 2020). "Importantly, the batch effect causes substantial differences in germline variant distribution patterns across numerous genes, including prominent cancer predisposition genes such as BRCA1, RET, MAX, and KRAS." (PMID 31391007, 2019). "Our data suggest that the MYC:TRRAP interaction could have a lower free energy of association, and therefore is a more desirable target for inhibition of MYC function in cancer by small-molecules than the MYC:MAX interphase." (PMID 31790487, 2019). "Mechanistically, MBZ can modulate several cancer-associated pathways, such as ELK1/SRF, AP1, STAT1/2, MYC/MAX, although the regulatory outcomes may be context-dependent." (PMID 28099902, 2017). "We identify MAX as a new cancer gene, particularly relevant to brain cancer." (PMID 27294413, 2016). "Transfection of malignant T cells with recombinant miR-22 inhibits the expression of validated miR-22 targets including NCoA1, a transcriptional co-activator in others cancers, as well as HDAC6, MAX, MYCBP, PTEN, and CDK2, which have all been implicated in CTCL pathogenesis." (PMID 26244872, 2015). "As a result, we speculated that tobacco smoke might induce cancer by targeting genes such as MAX and USF1." (PMID 26629988, 2015). "In the human network, we also found a significant enrichment for developmental signaling pathways, exemplified by proteins like ID3 and UNC45A, which are involved in cell differentiation and proliferation, and which interact with the cancer drivers MAX and TCF12 respectively." (PMID 26576632, 2015). "We identified damaging mutations in ATR, BRCA1/2, MAP4K1, CUL3 and MAX, already reported in other cancer types but not described yet as mutated in PTC." (PMID 25803323, 2015). "In addition, GSCA also recovered associations with MAX and the MAX interacting protein MXI1, both of which have also been linked to a range of human cancers." (PMID 23220237, 2013). "We chose to analyze these genes in other types of cancers so as to detect if there was a general trend for their expression which could confirm our previous results with MAX and shed some light at TFEC." (PMID 24349289, 2013). "However, the identification of differential correlation structure provides the first integrated hypothesis that suggests MAX could modulate the co-expression of ATF4 and CLOCK, leading to differential cancer drug susceptibility." (PMID 26539209, 2015). "Therefore, MAX may also participate in the same or similar biological processes that affect the development and progression of cancers." (PMID 21985575, 2011). "In the Myc datasets (GSE22139, GSE11791), multiple top-ranked TFs, such as MAX, SP1, NRF1, and E2F4, are known to interact with MYC in regulating the expression of common target genes in cancer cells." (PMID 38032891, 2023).